CEP57 (centrosomal protein 57)
Description:
Centrosomal protein which may be required for microtubule attachment to centrosomes. May act by forming ring-like structures around microtubules. Mediates nuclear translocation and mitogenic activity of the internalized growth factor FGF2, but that of FGF1.
Synonyms: KIAA0092; TSP57; Translokin; MVA2; PIG8
Tractability: PROTAC: ubiquitination databases record sites on it; its protein half-life has been measured.
Gene: Protein-coding gene on chromosome 11 (95,789,965 to 95,832,693, forward strand). Ensembl gene ENSG00000166037.
Subcellular location: Nucleus; Cytoplasm; Cytoplasm, cytoskeleton, microtubule organizing center, centrosome
Subcellular location (Human Protein Atlas): Centrosome; Centriolar satellite; Cytosol
Pathways (Reactome):
Cell Cycle: AURKA Activation by TPX2; Loss of Nlp from mitotic centrosomes; Loss of proteins required for interphase microtubule organization from the centrosome; Recruitment of NuMA to mitotic centrosomes; Recruitment of mitotic centrosome proteins and complexes; Regulation of PLK1 Activity at G2/M Transition
Organelle biogenesis and maintenance: Anchoring of the basal body to the plasma membrane
Gene Ontology:
Molecular function: fibroblast growth factor binding; protein binding; protein homodimerization activity; microtubule binding; gamma-tubulin binding; identical protein binding
Biological process: fibroblast growth factor receptor signaling pathway; spermatid development; protein homooligomerization
Cellular component: centrosome; cytosol; Golgi apparatus; microtubule; nucleus; cytoplasm
Genetic constraint (gnomAD): Loss-of-function variants: 34 observed, 61.14 expected, observed/expected ratio (o/e) 0.56, 90% interval 0.42 to 0.74. The upper end of that interval is the gene's LOEUF score, 0.74, which puts it in group 3 of 6, group 1 being the genes least tolerant of losing a copy. Missense variants: 581 observed, 584.34 expected, observed/expected ratio (o/e) 0.99, 90% interval 0.93 to 1.07. Synonymous variants: 215 observed, 204.16 expected, observed/expected ratio (o/e) 1.05, 90% interval 0.94 to 1.18.
Gene-disease validity (ClinGen):
ClinGen rates the evidence that CEP57 causes each of these diseases.
mosaic variegated aneuploidy syndrome 2 (autosomal recessive): Definitive. Any mosaic variegated aneuploidy syndrome in which the cause of the disease is a mutation in the CEP57 gene.
Homologues: Orthologues: chimpanzee CEP57 (99% identical), macaque CEP57 (95% identical), dog CEP57 (91% identical), rabbit CEP57 (90% identical), mouse Cep57 (88% identical), guinea pig CEP57 (86% identical), rat Cep57 (86% identical), tropical clawed frog cep57 (54% identical). Paralogues in human: CEP57L1 (30% identical).
Diseases named in the same sentence as CEP57 in open-access papers:
CEP57 is named in the same sentence as 26 diseases in open-access papers, as found by Europe PMC text mining. Sharing a sentence is not in itself a finding about the gene and the disease. The quoted sentences say what the papers report.
childhood cancers (3 papers, 2018 to 2020). "CEP57 encodes a 57 kDa member of the CEP family of centrosomal proteins involved in MVA2, a rare pediatric syndrome with high risk of development of childhood cancers." (PMID 29659569, 2018). "Typical symptoms of the known MVA syndromes caused by mutations in BUBR1, CEP57, and TRIP13 are intrauterine growth retardation, mental retardation, microcephaly, and childhood cancer, none of which were observed in the patient." (PMID 33094908, 2020). "The observed spontaneous and DMBA-induced cancer phenotypes in Cep57-insufficient mice were unexpected because MVA patients with CEP57 mutations, in contrast to those carrying mutations in BUBR1 and TRIP13, are not known to be predisposed to childhood cancers." (PMID 30035751, 2018).
microcephaly (3 papers, 2015 to 2020). A congenital or acquired developmental disorder in which the circumference of the head is smaller than normal for the person's age and sex. "Studies of mosaic variegated aneuploidy (MVA) patients harboring mutations in Bub1b and Cep57 also showed aneuploidy and microcephaly." (PMID 26044958, 2015). "However, CEP57 mutant lymphoblasts from one MVA patient were recently found to be SAC-proficient, so that the relative contribution of centrosomal and kinetochore defects in CEP57-mutated microcephaly is still unclear." (PMID 31878213, 2019).
prostate carcinoma (3 papers, 2018 to 2021). A carcinoma that arises from epithelial cells of the prostate gland. "RPS25 was shown to be a potential biomarker of lung adenocarcinoma and adult T-cell leukemia, while CEP57 was associated with prostate cancer." (PMID 34208938, 2021). "Interestingly, CEP57 insufficiency correlates with tumor growth and metastasis in 2 prostate cancer patient cohorts, and monoallelic mutation was reported in early-onset familial prostate cancers." (PMID 30035751, 2018).
aneuploidy (1 paper, 2024). Chromosomal disorder consisting of the presence a chromosomal abnormality in which there is an addition or loss of chromosomes within a set. "Genetic truncation mutations of Cep57 are associated with the mosaic-variegated aneuploidy (MVA) syndrome." (PMID 38857398, 2024). "Mutations in Cep57 are linked to mosaic-variegated aneuploidy (MVA) syndrome." (PMID 38857398, 2024).
ciliopathy (1 paper, 2019). A genetic disorder of the cellular cilia or the cilia anchoring structures, the basal bodies, or of ciliary function. "For most proteins, the trend reflected results from the WCP (i.e. PLK4 is up‐, whereas CEP63 and CEP57 down‐regulated) with the ciliopathy‐associated proteins CEP41 and CENPF being notable exceptions." (PMID 31304626, 2019).
diabetic (1 paper, 2025). "Importantly, our data reveal that the AGE–KLF5–KLHL13–CUL3 axis specifically regulates CEP57L1 without affecting its paralog CEP57, highlighting a nonredundant and pathway-specific role for CEP57L1 in this diabetic cancer context." (PMID 41443421, 2025).
emphysema (1 paper, 2021). "The FEV1pp miRNA–mRNA networks and percent emphysema network share three genes (CAPZA1, CEP57, and SLC15A3) and eight miRNAs including hsa-miR-145-5p, hsa-miR-223-3p, hsa-miR-26b-3p, hsa-miR-338-5p, hsa-miR-1275, hsa-miR-150-3p, hsa-miR-150-5p, and hsa-miR-342-3p." (PMID 34777474, 2021).
lung adenoma (1 paper, 2018). A benign, well circumscribed epithelial neoplasm that arises from the bronchus or the lung parenchyma. "FISH analysis indicated that Cep57+/T lung adenomas were significantly more aneuploid than flanking normal lung tissue." (PMID 30035751, 2018). "All 7 lung adenomas analyzed showed centrosomal Cep57 labeling in both tumorous and normal lung tissue." (PMID 30035751, 2018). "To this end, we prepared lysates of dissected lung adenomas and corresponding normal lung tissue, and analyzed Cep57 protein levels by Western blot analysis." (PMID 30035751, 2018). "In contrast, 65% of Cep57+/T mice had tumors at 16 months, with lung adenomas being the most prevalent tumor type." (PMID 30035751, 2018). "At 16 months of age, Cep57+/– mice showed markedly increased tumor formation compared with Cep57+/+ littermates, with lung adenomas again being the most common tumor type." (PMID 30035751, 2018). "Furthermore, centrosome amplification and formation of micronuclei, 2 characteristics of the chromosomal instability phenotype of Cep57+/T MEFs, occurred at significantly higher rates in Cep57+/T lung adenomas than in their Cep57+/+ counterparts." (PMID 30035751, 2018).
primordial dwarfism (1 paper, 2019). "Microcephaly osteodysplastic primordial dwarfism disease pericentrin mutations impair the Cep57-pericentrin interaction and lead to PCM disorganization." (PMID 30804344, 2019). "Importantly, microcephaly osteodysplastic primordial dwarfism disease-related PCNT mutations impair the Cep57–PCNT interaction and lead to PCM disorganization." (PMID 30804344, 2019).
Seckel syndrome (1 paper, 2018). A rare autosomal recessive inherited syndrome caused by mutations in the ATR gene, RBBP8 gene, CENPJ gene, CEP152 gene, CEP63 gene, NIN gene, DNA2 gene, or TRAIP gene. "Interestingly, mutations in CEP63, CEP152, and PLK4, but not CEP57, are associated with Seckel syndrome or autosomal recessive primary microcephaly syndrome, indicating that CEP57 and its binding partners have nonredundant functions." (PMID 30035751, 2018).
cancer (5 papers, 2018 to 2025). A tumor composed of atypical neoplastic, often pleomorphic cells that invade other tissues. "Given that aneuploidy rates are elevated in Cep57-haploinsufficient mice and that cancer is a potential outcome of aneuploidy, it is tempting to speculate that the observed chromosomal instability and cancer phenotypes are causally linked." (PMID 30035751, 2018). "We finally obtained eight bona fide cancer driver genes, including CEP57, HNRNPL, KLF5, OXA1L, PAFAH1B1, RBM39, SYT13, and TFDP1." (PMID 31925297, 2020). "Accordingly, mosaic variegated aneuploidy syndrome (MVA) patients, who have mutations in the centrosomic protein CEP57 or in the SAC protein BUBR1, are highly susceptible to childhood cancers, further underscoring that ongoing CIN predisposes to cancer." (PMID 32873156, 2020). "Cep57+/T and Cep57+/– mice, on the other hand, had milder chromosomal instability phenotypes and were cancer prone." (PMID 30035751, 2018). "BUBR1 and TRIP13, but not CEP57, have a common role in the mitotic checkpoint, which has been linked to the separation in cancer phenotypes among MVA syndrome patients." (PMID 30035751, 2018). "Mice heterozygous for the truncating frameshift mutation or a Cep57-null allele were overtly indistinguishable from WT mice despite reduced Cep57 protein levels, yet prone to aneuploidization and cancer, with tumors lacking evidence for loss of heterozygosity." (PMID 30035751, 2018). "CEP57 (or translokin) was originally identified as a microtubule-binding protein that mediates nuclear translocation of FGF2 in aortic endothelial cells and cancer cell lines." (PMID 30035751, 2018).
tumor (3 papers, 2018 to 2021). "Collectively, these results demonstrate that Cep57T is a partially functional allele, and that Cep57 is a multifunctional protein with important roles in centrosome maturation, tumor suppression, and Fgf2-mediated skeletal development." (PMID 30035751, 2018). "The tumor spectrum was the same between both genotypes, suggesting that Cep57 mutation accelerates the progression of neoplastic lesions that mice on a 129 × C57BL/6 genetic background normally develop." (PMID 30035751, 2018). "In summary, we discovered that Cep57 is implicated in 2 diverse biological processes, bone formation and tumor suppression." (PMID 30035751, 2018). "To determine whether carriers of the Cep57T mutation are tumor prone, we established cohorts of Cep57+/T and Cep57+/+ littermates and screened these mice for tumors at 16 months of age." (PMID 30035751, 2018). "The fold increase in tumor incidence was strikingly similar between Cep57+/T and Cep57+/– mutant mice." (PMID 30035751, 2018). "Cep57+/+ mice had a tumor incidence of 24%, which is consistent with tumor rates in control cohorts in previously reported studies." (PMID 30035751, 2018). "This study identifies Cep57 as a haploinsufficient tumor suppressor with biologically diverse roles in centrosome maturation and Fgf2-mediated bone formation." (PMID 30035751, 2018). "Third, we established that Cep57 is a haploinsufficient tumor suppressor." (PMID 30035751, 2018). "FGF2 is a pleiotropic growth factor involved in embryonic development, wound healing, angiogenesis, and tumor progression, but whether CEP57 is important for any of these biological functions is unclear." (PMID 30035751, 2018). "We complemented these spontaneous tumorigenesis studies with a tumor bioassay in which a single dose of the carcinogen 7,12-Dimethylbenz[a]anthracene (DMBA) was applied to the dorsal skin of Cep57+/T and Cep57+/+ littermate pups at postnatal day 6 (P6)." (PMID 30035751, 2018). "Our analysis of Cep57+/T mice did not provide conclusive evidence that reduced Cep57 expression drives tumorigenesis, because the possibility that the presence of Cep57T protein is a requirement for tumor development cannot be ruled out." (PMID 30035751, 2018). "Taken together, these results indicate that Cep57 is a haploinsufficient rather than a classical tumor suppressor." (PMID 30035751, 2018).
genetic disorder (1 paper, 2020). "Mosaic variegated aneuploidy (MVA) is a rare genetic disorder caused by mutations in BUB1B, CEP57, or TRIP13." (PMID 32884756, 2020).
CEP57 also shares sentences with these, for which no sentence is quoted: adult T-cell leukemia (1 paper); astrocytoma (1); atypical teratoid rhabdoid tumor (1); ependymoma (1); Ewing sarcoma (1); familial prostate cancers (1); leukemia (1); lung adenocarcinoma (1); lymphoma (1); neuroblastoma (1); rhabdomyosarcoma (1); sarcopenia (1); Warsaw breakage syndrome (1).